HDAC5 (histone deacetylase 5)
Diseases named in the same sentence as HDAC5 in open-access papers (continued):
Sharing a sentence is not in itself a finding about the gene and the disease.
myocardial infarction (2 papers, 2014 to 2019). Gross necrosis of the myocardium, as a result of interruption of the blood supply to the area, as in coronary thrombosis. "Female mice lacking HDAC5 or HDAC9 are protected from post-myocardial infarction (MI) remodeling due to enhanced estrogen receptor-mediated transcription of proangiogenic genes in the heart whereas male knockout mice die at a higher frequency post-MI." (PMID 24608696, 2014).
pancreatic ductal adenocarcinoma (2 papers, 2025 to 2026). An infiltrating adenocarcinoma that arises from the epithelial cells of the pancreas. "Rationale: Loss of histone deacetylase 5 (HDAC5) is frequently observed in multiple malignancies, including pancreatic ductal adenocarcinoma (PDAC), and is associated with poor patient survival." (PMID 41608562, 2026). "A study reported that, in pancreatic ductal adenocarcinoma, histone deacetylase 5 (HDAC5) suppresses the transcriptional activity of NF-κB by directly interacting with p65 and mediating deacetylation at K310, thereby regulating PD-L1 expression." (PMID 41035656, 2025).
pulmonary arterial hypertension (2 papers, 2019 to 2023). Pulmonary arterial hypertension (PAH) is a group of diseases characterized by mean pulmonary artery pressure >20 mmHg and elevated pulmonary arterial resistance leading to right heart failure. "In contrast, increased expression of HDAC3, HDAC4, and HDAC5 is associated with induction of Nox2 and Nox4 in pulmonary arterial hypertension, which was decreased by the HDAC inhibitor, valproic acid." (PMID 31223486, 2019). "The transcriptional activity of MEF2 in PAECs from pulmonary artery hypertension (PAH) patients was impaired by the increased nuclear localization of HDAC4 and HDAC5." (PMID 37008050, 2023).
scleroderma (2 papers, 2022 to 2024). Scleroderma is a rare autoimmune connective tissue disorder characterized by abnormal hardening of the skin and, sometimes, other organs. "Additionally, HDAC5 has been implicated in impaired angiogenesis, a hallmark of scleroderma (SSc)." (PMID 38987624, 2024). "Besides, deficiency of HDAC5 in endothelial cells of patients with Scleroderma increases FSTL1 expression and improves the ability of endothelial cells to form tubules in Matrigel, suggesting that FSTL1-mediated promotion of angiogenesis is dependent on HDAC5." (PMID 36091401, 2022).
systemic sclerosis (2 papers, 2020 to 2022). A chronic disorder, possibly autoimmune, marked by excessive production of collagen which results in hardening and thickening of body tissues. "In addition, HDAC5 played an important role in inhibiting expression of the genes participating in angiogenesis including CYR61, PVRL2, FSTL1, and Slit2 in patients with systemic sclerosis, which could be reversed by silencing of HDAC5." (PMID 33282862, 2020).
type 2 diabetes (2 papers, 2022 to 2024). "However, acetate, through suppression of the increased circulating and hypothalamic HDAC5 in fructose-induced type 2 diabetes mellitus (T2DM) rats, may attenuate metabolic syndrome in the affected animals." (PMID 39199231, 2024).
adenoma (1 paper, 2013). A neoplasm arising from the epithelium. "We performed a PCR array for HDAC1, HDAC2, HDAC3, HDAC5 and HDAC7 on human rectal biopsies from patients with or without an adenoma in the colon (n = 86 subjects total)." (PMID 23724067, 2013).
age-related macular degeneration (1 paper, 2015). Age-related loss of vision in the central portion of the retina (macula), secondary to retinal degeneration. "Human neural retina concentrations of HDAC1, 2, HDAC5, HDAC6, and HDAC7 decreased in age-related macular degeneration (AMD)-affected donors and exhibited a greater decrease in AD-affected donors in comparison to age-matched control neural retinas." (PMID 25962138, 2015).
alcoholism (1 paper, 2023). "Genes highlighted in alcoholism were related to ethanol signaling to histones H3 and H4 acetylation that involve genes such as Hdac5, H2ac12, H3c7, and H4c3." (PMID 37443838, 2023).
Alzheimer disease (1 paper, 2016). A progressive, neurodegenerative disease characterized by loss of function and death of nerve cells in several areas of the brain leading to loss of cognitive function such as memory and language. "HDAC5 is involved in memory consolidation and targeting HDAC5 has been suggested to be avoided for the development of more selective HDAC inhibitors to treat Alzheimer’s disease." (PMID 26747087, 2016).
anaplastic oligoastrocytoma (1 paper, 2021). An oligoastrocytoma characterized by the presence of increased cellularity, nuclear atypia, pleomorphism, and high mitotic activity. "The comparisons of HDAC5 expression between anaplastic oligoastrocytoma (n = 6), anaplastic oligodendroglioma (n = 3), GBM (n = 27), and normal (n = 4) exposed a 2.10-fold (p = 4.64E-05), 2.44-fold (p = 0.003), 2.38-fold (p = 1.46E-07) decrease, respectively." (PMID 34540896, 2021).
Arthritis (1 paper, 2025). Inflammation of a joint. "Overall, these results indicate that HDAC5-overexpressing MSCs have strong therapeutic potential for arthritis in an inflammatory microenvironment." (PMID 41436435, 2025). "In addition, MSCs overexpressing HDAC5 successfully prevented TNF-α-induced impairment of immunosuppressive function and improved therapeutic effects in an SKG arthritis model." (PMID 41436435, 2025).
Atrophy (1 paper, 2014). Any weakening or degeneration, especially through lack of use. "In particular, the determination of protein level of the two IGF-1 sensitive genes MuRF1 and HDAC5 would deserve a focused investigation, also if it has been found that the MuRF1 mRNA modification during atrophy is often accompanied by corresponding changes in protein levels." (PMID 23755187, 2014).
bipolar disorder (1 paper, 2021). A disorder of the brain that causes unusual shifts in mood, energy, activity levels and the ability to carry out day-to-day tasks. "Also, only CEWAS found FAHD2B, HDAC5, MBTD1, NME2, and XPNPEP3 for bipolar disorder." (PMID 34807913, 2021).
cardiomyopathy (1 paper, 2025). A disease of the heart muscle or myocardium proper. "Our data demonstrate that inhibition of HDAC5 effectively reverses TTN-silencing-induced gene dysregulation, thereby identifying HDAC5 as a promising therapeutic target in TTN-deficient related cardiomyopathy." (PMID 41283336, 2025). "Although the precise mechanisms remain to be clarified, the ability of pharmacological HDAC5 inhibition with TMP-195 to reverse TTN-deficiency-induced gene dysregulation highlights its promising translational potential for TTN-related cardiomyopathies." (PMID 41283336, 2025). "In summary, our findings support the therapeutic potential of selective HDAC5 inhibition for TTN-related cardiomyopathies." (PMID 41283336, 2025). "Importantly, this regulation extends beyond contractile function to fibrotic remodeling, underscoring the multifaceted role of HDAC5 in TTN-related cardiomyopathies." (PMID 41283336, 2025). "Thus, placing our findings within this broader framework underscores that epigenetic targeting of HDAC5 may have implications not only for inherited cardiomyopathies but also for cardiovascular remodeling more generally." (PMID 41283336, 2025). "By contrast, in cardiomyopathy patients, Class II HDACs including HDAC5 expression remain largely unchanged, implying that this group of HDACs may act in a context- or signal-dependent manner in patients (for example, being pathologically activated without a change in steady-state expression)." (PMID 41283336, 2025). "The pivotal role of TTN in cardiomyopathies, together with the emerging importance of epigenetic regulation, raises the possibility that the interplay between TTN and HDAC5 could provide new insights into disease pathogenesis." (PMID 41283336, 2025). "Thus, NPPA regulation in cardiomyopathy likely integrates both stress-induced signaling and HDAC-mediated chromatin regulation, highlighting that HDAC5 inhibition may reinforce endogenous cardioprotective responses." (PMID 41283336, 2025).
chromophobe carcinoma (1 paper, 2021). "For example, in RCC (including chromophobe carcinoma, ccRCC, and papillary cell carcinoma), low expression of HDAC1, HDAC2, HDAC3, HDAC8, HDAC10 and high expression of HDAC5, HDAC7, HDAC11 have longer survival time." (PMID 34308568, 2021).
chronic obstructive pulmonary disease (1 paper, 2017). A chronic and progressive lung disorder characterized by the loss of elasticity of the bronchial tree and the air sacs, destruction of the air sacs wall, thickening of the bronchial wall, and mucous accumulation in the bronchial tree. "For instance, it has been demonstrated that the massage levels of HDAC5, among other class I and class II HDACs, are down-regulated in the lungs in patients with chronic obstructive pulmonary disease (COPD)." (PMID 29212224, 2017).
Cognitive impairment (1 paper, 2021). Abnormal cognition is characterized by deficits in thinking, reasoning, or remembering. "An intriguing application of our data is that HDAC5 and other epigenetic enzymes may serve as a critical link between psychiatric disorders and associated cognitive impairment." (PMID 34716230, 2021).
cowpox (1 paper, 2024). A mild, eruptive skin disease of milk cows caused by cowpox virus, with lesions occurring principally on the udder and teats. "The antiviral activity of HDAC5 is antagonized by VACV protein C6 and orthologs from the orthopoxviruses cowpox, rabbitpox, camelpox, monkeypox, and variola." (PMID 38461415, 2024).
epilepsy (1 paper, 2021). A brain disorder characterized by episodes of abnormally increased neuronal discharge resulting in transient episodes of sensory or motor neurological dysfunction, or psychic dysfunction. "microRNA.org and Starbase predicted that miR-485 targeted HDAC5 both in human and mouse, and we found increased HDAC5 expression in the hippocampal neuron model of epilepsy." (PMID 34021541, 2021). "Taken together, these results indicate that miR-485 inhibited apoptosis, oxidative stress, and inflammation by targeting and inhibiting HDAC5 in epilepsy model neurons." (PMID 34021541, 2021). "Taken together, these results show that miR-485 inhibited epilepsy through the HDAC5/HIF1α/PFKFB3 axis in vivo." (PMID 34021541, 2021). "Following upon that precedent, we proposed in this study to investigate a possible relationship between miR-485 and the expression of HDAC5, which we predict to be a downstream signaling molecule of miR-485-related epilepsy." (PMID 34021541, 2021). "HDAC5 silencing reduced apoptosis in epilepsy model cells, which was reversed by HIF1α or PFKFB3 overexpression." (PMID 34021541, 2021). "In conclusion, miR-485 alleviates epilepsy through inhibition of HDAC5, leading to downregulation of HIF1α and PFKFB3." (PMID 34021541, 2021). "HDAC5 silencing decreased HDAC5 expression in the hippocampal neuron model of epilepsy, as did treatment with miR-485 mimic, an effect which was reversed by HADC5 overexpression." (PMID 34021541, 2021). "Given the involvement of PFKFB3 is involved in neuronal excitotoxicity, which is an important mechanism for epilepsy, we set about to investigate the interactions among miR-485, with HDAC5, HIF1α, and PFKFB3 in cellular and animal models of epilepsy." (PMID 34021541, 2021). "We proceeded in our study to investigate the downstream signaling molecules involved in miR-485-related epilepsy, which showed that miR-485 bound to and inhibited HDAC5 expression." (PMID 34021541, 2021). "Overall, miR-485 inhibited apoptosis, oxidative stress, and inflammation in epilepsy model cells through the HDAC5/HIF1α/PFKFB3 axis." (PMID 34021541, 2021). "Hypoxia-inducible factor-1alpha (HIF1α) is a pro-inflammatory downstream mediator of HDAC5, which can promote epilepsy." (PMID 34021541, 2021). "HDAC5 silencing or miR-485 mimic reduced apoptosis in epilepsy model neurons, while HDAC5 overexpression reversed the effect of miR-485 mimic." (PMID 34021541, 2021). "miR-485 was downregulated and HDAC5 was upregulated in cell and animal model of epilepsy." (PMID 34021541, 2021). "Thus, miR-485 alleviates neuronal damage and epilepsy by inhibiting HDAC5, HIF1α, and PFKFB3." (PMID 34021541, 2021). "Collectively, we find that miR-485 alleviates epilepsy by inhibiting HDAC5, HIF1α, and PFKFB3 expression, thus presenting therapeutic targets for the treatment of epilepsy." (PMID 34021541, 2021). "The forced HDAC5 overexpression increased HDAC5, HIF1α, and PFKFB3 expression in the presence of miR-485 mimic in epilepsy model cells, but increased HIF1α and PFKFB3 expressions only in the presence of miR-485 mimic." (PMID 34021541, 2021). "HDAC5 silencing or miR-485 mimic reduced the formation of IL-1β, TNF-α, and IL-6 by epilepsy model neurons, and this effect was rescued by HDAC5 overexpression." (PMID 34021541, 2021). "HDAC5 silencing or miR-485 mimic increased SOD and GSH-Px expression, while decreasing the concentrations of MDA and DNA 8-OHdG in epilepsy model cells." (PMID 34021541, 2021). "miR-485 mimic reduced HDAC5, HIF1α, and PFKFB3 expressions in epilepsy model cells." (PMID 34021541, 2021).
Glucose intolerance (1 paper, 2024). Glucose intolerance (GI) can be defined as dysglycemia that comprises both prediabetes and diabetes. "Of note, the obese phenotype of HDAC5 KOs occurs under non-obesogenic conditions, and is accompanied by hyperleptinemia, glucose intolerance and dyslipidemia, all of which are typical hallmarks for the metabolic syndrome." (PMID 39304061, 2024).
head and neck cancer (1 paper, 2023). A primary or metastatic malignant neoplasm affecting the head and neck. "To investigate the role of class IIa HDACs in head and neck cancer and possible implications for chemoresistance, we generated stable HDAC4 and HDAC5 overexpression clones by lentiviral transduction." (PMID 36982651, 2023). "Taken together, neither HDAC4 nor HDAC5 expression status nor class IIa HDAC inhibition had a notable influence on cisplatin sensitivity in the head and neck cancer cell lines Cal27 and Cal27CisR (shift factors < 2) in contrast to results with vorinostat." (PMID 36982651, 2023).
Hepatic fibrosis (1 paper, 2019). The presence of excessive fibrous connective tissue in the liver. "Top canonical pathways identified by Ingenuity Pathway analysis (IPA) included axonal guidance, a process well-known to be influenced by HDAC5 and hepatic fibrosis (see Discussion)." (PMID 31052182, 2019). "Indeed, analysis of transcriptomics data from the HDAC5-transduced UC cell lines by IPA highlighted parallels between the effects of HDAC5, hepatic fibrosis, TGFβ and TNFα signaling." (PMID 31052182, 2019).
inflammatory bowel disease (1 paper, 2025). A spectrum of small and large bowel inflammatory diseases of unknown etiology. "Although HDAC5 has not been linked to inflammatory bowel disease (IBD) in genetic studies, histone deacetylases more broadly have been implicated in disease pathogenesis through epigenetic and functional analyses." (PMID 40832175, 2025).
ischemia (1 paper, 2017). A hypoperfusion of the BLOOD through an organ or tissue caused by a PATHOLOGIC CONSTRICTION or obstruction of its BLOOD VESSELS, or an absence of BLOOD CIRCULATION. "The results suggest that both HDAC5 and p300 are involved in MRTF-A-mediated effect on neuronal apoptosis during ischemia/reperfusion injury, but with opposite effects." (PMID 28230854, 2017).
leukemia (1 paper, 2022). A malignant (clonal) hematologic disorder, involving hematopoietic stem cells and characterized by the presence of primitive or atypical myeloid or lymphoid cells in the bone marrow and the blood. "HDAC5, up-regulated in the NBDG-low population, may lead to the maintenance of quiescence in leukemia initiating cells." (PMID 36212452, 2022).
liver disease (1 paper, 2021). "The main findings of our study are as follows: First, decreased HDAC4 and HDAC5 levels were identified in livers of tx-j mice starting at early stages of hepatic copper accumulation and progressing with age-related worsening of liver disease." (PMID 34098115, 2021). "Ultimately, class IIa HDAC4 and HDAC5, as key metabolic elements, represent a regulatory interface between genetic and metabolic factors affecting the varied phenotypic presentations and liver disease manifestations in WD." (PMID 34098115, 2021).
memory impairment (1 paper, 2014). "Thus, at present it appears that HDAC2 and HDAC6 are the most suitable drug targets to treat memory impairment in AD, while inhibition of HDAC5 should be avoided." (PMID 25009454, 2014). "Deletion of HDAC5 in 2-month old mice does not cause memory impairments." (PMID 25009454, 2014).
muscular dystrophies (1 paper, 2022). "Among these candidate genes were DNAJB12, HDAC5, and TRIM8, each belonging to a protein family that is being studied in the context of neurological disorders or muscular dystrophies." (PMID 36352383, 2022).
Osteopenia (1 paper, 2016). Osteopenia is a term to define bone density that is not normal but also not as low as osteoporosis. "Second, anti-sclerostin antibody treatment rescued the trabecular osteopenia present in HDAC5−/− animals, which have high levels of SOST expression." (PMID 27759007, 2016).
pancreatic neuroendocrine tumor (1 paper, 2018). Pancreatic endocrine tumor, also known as pancreatic neuroendocrine tumor (PNET), describes a group of endocrine tumors originating in the pancreas that are usually indolent and benign, but may have the potential to be malignant. "Analysis of expression patterns in pancreatic neuroendocrine tumors (pNETs) indicated HDAC5 to be a potential target for future therapies." (PMID 30321986, 2018).
pheochromocytoma (1 paper, 2021). "Here we report that exposure of rat pheochromocytoma (PC)-12 cells to IH in vitro exhibited reduced HDAC enzyme activity due to proteasomal degradation of HDAC3 and HDAC5 proteins." (PMID 34079475, 2021).
posttraumatic stress disorder (1 paper, 2022). "Indeed, we have previously shown that male rats exposed to single prolonged stress, a model of posttraumatic stress disorder (PTSD), and displaying deficient fear-extinction memory recall had decreased HDAC4 and HDAC5 levels in the HC, but not the striatum." (PMID 36540409, 2022).
pterygium (1 paper, 2022). A wedge-shaped fibrovascular lesion arising from the bulbar conjunctiva and extending to the cornea. "Furthermore, we have found that the expression of multiple epigenetic regulators was upregulated in the 3D pterygium model, including DNA methyltransferase DNMT3B, lysine demethylase KDM6B, and histone deacetylase HDAC5." (PMID 35101743, 2022).
Renal cyst (1 paper, 2019). A fluid filled sac in the kidney. "It shows that Hdac5 inhibition reduces renal cyst formation and improves renal function in an adult ADPKD model." (PMID 31059522, 2019).
retinoblastoma (1 paper, 2025). A malignant tumor that originates in the nuclear layer of the retina. "Retinoblastoma (RB) promotes histone deacetylation and gene silencing via recruiting HDAC5 or HDAC1 under different circumstances." (PMID 40659605, 2025).
skin cancer (1 paper, 2025). "Our findings demonstrated a generalized upregulation of HDAC5 and HDAC6 genes in HaCaT, HepG2, and A549 after treatment exposure with TRZ, indicating that HDAC5 and HDAC6 are potential lung, liver, and skin cancers therapeutic targets and prognostic biomarkers." (PMID 40077783, 2025).